LGALS3 (galectin 3)
Diseases named in the same sentence as LGALS3 in open-access papers (continued):
Sharing a sentence is not in itself a finding about the gene and the disease.
liver disease (42 papers, 2012 to 2025). "Galectin 3 (Gal-3) is up-regulated in several liver disorders suggesting its implication in the mechanisms underlying liver damage." (PMID 40608687, 2025). "Galectin-3 is widely expressed throughout the body and elevated concentration is implicated in kidney disease, heart disease, and liver disease." (PMID 36959138, 2023). "BNP and galectin-3 are associated with the severity of portal hypertension in cirrhotic cardiomyopathy." (PMID 37513890, 2023). "Lgals3−/− mice aged six months showed significant liver disorders associated with high circulating levels of ALT, triglycerides, and liver lipid peroxide." (PMID 31337151, 2019). "Using a comprehensive panel of circulating organokines, including fibroblast growth factor (FGF) 19, FGF21, adiponectin, galectin-3, irisin, and leptin, along with choline metabolites, we characterized metabolic signaling patterns associated with liver disease severity." (PMID 40943431, 2025). "Initial studies to identify the anti-inflammatory and anti-fibrotic activities of galectin-3 were conducted using HSCs, macrophages, and animal models of liver disease." (PMID 40004240, 2025). "LGALS3 is a stable biomarker with elevated expression levels in many diseases, including heart, kidney, and liver disorders, as well as cancer." (PMID 39794359, 2025). "PSC is a liver disease associated with IBD, and serum galectin-3 was higher in PSC compared to IBD patients and healthy controls." (PMID 38731984, 2024). "They showed that BNP, galectin-3, and parameters of diastolic dysfunction were significantly increased according to the severity of portal hypertension and cirrhosis, with significant differences between the three groups." (PMID 37513890, 2023). "Elevation in galectin-3 as seen in worsening liver disease was found to be pro-fibrotic and pro-inflammatory predisposing to increase the risk of AFib." (PMID 37288203, 2023). "The suggestion is that measuring the level of galectin-3 can be a predictive value to monitor for the possible onset of new AFib in patients with advanced liver disease." (PMID 37288203, 2023). "A galectin-3 inhibitor, belapectin, exhibited a significant effect on portal hypertension and the development of varices in a subgroup of patients without varices at baseline." (PMID 35453652, 2022). "Current studies also suggested that galectin-3 can be used as a target to regulate the function of inflammatory macrophages in advanced liver diseases, and galectin-3 inhibitors are under clinical investigations." (PMID 35990625, 2022). "Galectin-3 (GAL3) has been reported to be critically involved in the pathogenesis of multiple liver diseases, whereas the potential role of GAL3 in ACLF remains to be explored." (PMID 36075893, 2022). "Galectin-3 is one of the most frequently identified markers of liver disease and is considered a prognostic biomarker in severe trauma or sepsis patients." (PMID 32290120, 2020). "Galectin-3 plays very important roles in the pathogenesis of inflammatory liver diseases and liver malignancies." (PMID 32707678, 2020). "Of these disease-associated proteins and proteins related to Galectin-3, NDRG1 showed a close relationship to carcinoma and liver diseases, and CD166, S100A11 and Galectin-1 were also related to carcinoma." (PMID 28701735, 2017). "In this Section, we will therefore provide insights into the roles of galectin-3 in liver disease." (PMID 40649879, 2025). "Additionally, galectin-3 interacts with the CD98hc and β1-integrin complex, mediating inflammatory responses, thus playing a central role in the fibrotic processes of liver diseases like MASLD and MASH." (PMID 40004240, 2025). "In addition, this study adds further to the validation of galectin-3 as a therapeutic target in liver disease, supporting the ongoing clinical development of selvigaltin." (PMID 39144627, 2024).
liver disease (continued). "Inhibition of galectin-3 in liver disease is hypothesized to offer therapeutic potential, with early clinical studies starting to demonstrate effects on biomarkers of liver injury." (PMID 39144627, 2024). "This implies that galectin-3 inhibitors may exert a beneficial therapeutic effect on cirrhotic cardiomyopathy because portal hypertension is an important mechanism of cirrhotic cardiomyopathy." (PMID 37513890, 2023). "Another major finding of this study was that higher serum galectin-3 level was associated with an increased risk of liver failure, liver cirrhosis, and chronic active hepatitis B. Other evidence was also in favor of the importance of galectin-3 in these liver diseases." (PMID 34778306, 2021). "Moreover, two genes (IL7R and LGALS3) are related to liver disease as they were manipulated in the literature of HCV and HCC." (PMID 22867264, 2012). "Our findings are in line with those previously reported showing that other lectins, such as galectin-3, are able to trigger NLRP3 activation in the context of liver diseases and influenza infection." (PMID 31906385, 2020). "Galectin-3 is a biomarker of cardiovascular fibrosis and disease, and ALT is an important biomarker for diagnosing liver disease and reflecting liver damages." (PMID 32092951, 2020). "Consequently, galectin-3 inhibitors offer a novel therapeutic strategy for mitigating fibrosis and inflammation in MASLD and preventing its progression to more severe liver diseases." (PMID 40004240, 2025). "In contrast Lgals3 may be a preferred marker for liver disease since we find that it is not substantially up regulated in the brain." (PMID 23094108, 2012).
Cirrhosis (40 papers, 2009 to 2025). A chronic disorder of the liver in which liver tissue becomes scarred and is partially replaced by regenerative nodules and fibrotic tissue resulting in loss of liver function. "In this study, TSP-1, Galectin-3, and Cystatin-C were found to be independent risk factors for death in patients with cirrhosis, whereas Albumin and Prealbumin were protective." (PMID 40417691, 2025). "A third study compared HBV- and HCV-caused cirrhosis and described increased galectin-3 in the latter cohort." (PMID 28661458, 2017). "Further, serum levels of Galectin-3 have been found to be significantly increased in patients with cirrhosis." (PMID 40738513, 2025). "In the normal liver, galectin-3 is expressed in bile duct cells, and the galectin-3 protein levels of bile duct cells also seem to be increased in cholestasis and cirrhosis." (PMID 38731984, 2024). "In the liver, galectin-3 expression was strongly induced in cirrhosis, and higher serum galectin-3 levels were reported in patients with chronic liver diseases of different etiologies when compared to liver-healthy controls." (PMID 37189804, 2023). "Galectin-3 has been identified as a pivotal regulator in the progression of hepatitis, hepatic fibrosis, cirrhosis, and HCC." (PMID 35203484, 2022). "Galectin-3 is a well-described profibrotic factor and most likely contributes to liver injury in cirrhosis." (PMID 28661458, 2017). "Galectin-3 is a profibrotic protein and, thus, most likely contributes to liver injury in patients with cirrhosis." (PMID 28661458, 2017). "In the liver, galectin-3 expression is induced in cirrhosis." (PMID 38731984, 2024). "In a rat model of cirrhosis due to bile duct ligation, N-Lac treatment could decrease the galectin-3 and TNF-α contents in the heart." (PMID 38275628, 2023). "There is no documented evidence that galectin-3 has an effect on hyperdynamic circulation in cirrhosis; therefore, galectin-3 inhibition mainly mediates its effects by reducing inflammation, oxidative stress, apoptosis and fibrosis in the cardiovascular system of cirrhosis." (PMID 37513890, 2023). "The exact role of galectin-3 for liver cirrhosis is not as clear, but its increased expression has been linked to accelerated cirrhosis development and deterioration of liver function." (PMID 35203484, 2022). "Liver transplantation remains the only curative option for some patients, but pharmacological blockage of galectin-3 may offer elegant approaches for inhibiting cirrhosis progression and HCC, thereby reducing needs for transplantation." (PMID 28423321, 2017). "While the mechanism for these effects on fibrosis and cirrhosis is presumed to be interaction of the drugs with the galectin-3 protein, the interactions with galectin molecules are complex and molecular events downstream of galectin proteins are poorly understood." (PMID 24130706, 2013). "In addition, LGALS3 plays significant roles in hepatitis, cirrhosis, and liver failure." (PMID 39794359, 2025). "Moreover, Galectin-3 was used as a prognostic marker of cirrhosis in HCV disease." (PMID 33381596, 2020). "Considering that COL1A2 is a collagen, we performed a correlation analysis between SOX4, LGALS3, SERPINE2, CD52, LPXN, and MPP6 and the progression of cirrhosis." (PMID 39194690, 2024). "Additionally, the scar-associated macrophages (SAMs) differentiated by markers such as TREM2, CD9, SPP1, TNFSF12, and LGALS3 and PDGFRA+ myofibroblasts had an increased proportion in patients with cirrhosis." (PMID 39889710, 2025). "Interestingly, among these key genes, LGALS3 is the hub gene in the PPI interaction network and is the only key gene that has been reported to regulate cirrhosis progression." (PMID 39194690, 2024). "Pre-clinical outcomes of a galectin-3 inhibitor, the GR-MD-02, indicated its success in reversing NASH with cirrhosis, supporting clinical development trials in future that target advanced fibrosis/cirrhosis with NASH." (PMID 37377968, 2023).
Alzheimer disease (39 papers, 2016 to 2026). A progressive, neurodegenerative disease characterized by loss of function and death of nerve cells in several areas of the brain leading to loss of cognitive function such as memory and language. "Genomic studies indicate that the number of galectin-1- and galectin-3-expressing microglial cells increases with age- or age-related disease (Alzheimer’s disease), reflecting an aging-associated rise in galectin concentrations within the CNS." (PMID 40429840, 2025). "Modified citrus pectin (MCP) modulates galectin-3, a key player in neuroinflammation linked to Alzheimer’s disease." (PMID 39727960, 2024). "LGALS3 genetic variation in the Gal-3 encoding gene has been associated with poorer neurocognitive function in patients with Alzheimer’s disease (AD)." (PMID 35875353, 2022). "Lastly, Galectin-3 may also be involved in the pruning of synapses during the neonatal period and in the early loss of synapses in Alzheimer diseases." (PMID 30930748, 2019). "In Alzheimer’s disease, high levels of galectin-3 exacerbate amyloid deposits and worsen the pathological outcomes of the disease." (PMID 40429840, 2025). "Galectin-3 is also released by activated microglia in neurodegenerative diseases, including Alzheimer’s disease, aging, and amyotrophic lateral sclerosis (ALS)." (PMID 40429840, 2025). "This study investigates MCP’s effect on reducing neuroinflammation and its impact on cognitive function in an Alzheimer’s dementia model, focusing on its role in galectin-3 inhibition." (PMID 39727960, 2024). "Modified citrus pectin (MCP) exerts its effects by inhibiting galectin-3, thereby downregulating the TLR4/MyD88/NF-κB signaling pathways implicated in Alzheimer’s disease." (PMID 39727960, 2024). "Increased galectin-3 expression in human brain samples has been documented in the pathology of different neurodegenerative diseases including Alzheimer’s disease (AD) and Huntington’s disease (HD)." (PMID 36115971, 2022). "We have previously shown that galectin-3 can contribute to full-blown inflammatory microglial response 6 h following LPS challenge in vitro, and be a detrimental component in Alzheimer’s disease pathogenesis." (PMID 33514389, 2021). "Up to now, serum galectin-3 levels have been discovered to be increased in Alzheimer's disease (AD), indicating the possibility of its involvement in cognitive impairment." (PMID 34900086, 2021). "Changes of galectin-3 in CSF and blood have been reported in neurodegenerative diseases including Alzheimer’s disease (AD), amyotrophic lateral sclerosis (ALS), and PD." (PMID 34827514, 2021). "Galectin-3 plays an important role in the pathogenesis of neuroinflammatory and neurodegenerative disorders, such as multiple sclerosis, Alzheimer’s disease, Parkinson’s disease, and Huntington’s disease." (PMID 32455781, 2020). "It has been recently shown that Galectin-3 appears to be involved in inflammatory response in neurodegenerative disorders such as Alzheimer’s disease, Parkinson’s disease, and Huntington’s disease." (PMID 32455781, 2020). "We performed this study to investigate the possibility of a definitive pattern of Galectin-3 (Gal-3) expression in the cerebrospinal fluid (CSF) and serum of Alzheimer’s disease (AD) and Amyotrophic Lateral Sclerosis (ALS) patients." (PMID 30008660, 2018). "LGALS3 has been reported to show altered patterns of expression in different neurodegenerative diseases like Alzheimer disease (AD), Parkinson’s disease (PD) and ALS." (PMID 30577465, 2018). "In Alzheimer’s disease, activated microglia expressing galectin-3 bind to TLR4 (Toll-like receptor 4), MerTK, and TREM2 (triggering receptor expressed on myeloid cells 2), which facilitates amyloid-beta clearance and promotes inflammatory responses associated with the disease." (PMID 40429840, 2025).
Alzheimer disease (continued). "Interestingly, LGALS3 was found increased in the cerebrospinal fluid of Alzheimer disease patients and involved in the unconventional secretion of these spreading aggregates in Alzheimer and Parkinson disease." (PMID 41145409, 2025). "Galectin-3 (Gal3) is both endogenously expressed as well as released by microglia in the brain in pathological conditions, particularly in Alzheimer’s disease (AD)." (PMID 41487996, 2025). "In addition, galectin-3 is identified as a potential endogenous ligand of TREM2 in Alzheimer’s disease (AD)." (PMID 39135069, 2024). "A recent study has found that LGALS3 inhibitor can attenuate allodynia in a mouse model of Alzheimer’s disease (AD), suggesting that sensory neuron-derived LGALS3 may promote allodynia through the microglial secretion of pro-nociceptive mediators." (PMID 39911230, 2024). "More importantly, in Alzheimer’s disease Galectin-3 appear to be one of the key molecules in microglial activation and Galectin-3 deletion in AD prone mice attenuate microglia associated TLR dependent immune response, amyloid β burden and improves cognitive functions." (PMID 32455781, 2020). "Furthermore, galectin-3 was a central upstream regulator of the microglial immune response, and it could drive pro-inflammatory activation of microglia in Alzheimer's disease." (PMID 33686023, 2021). "Patients with Alzheimer’s disease (AD), amyotrophic lateral sclerosis (ALD), and Parkinson’s disease (PD) expressed higher levels of galectin-3." (PMID 36008956, 2022).
papillary thyroid carcinoma (39 papers, 2003 to 2026). "LGALS3, known for promoting tumor growth and metastasis in TC, has shown significant associations with TC susceptibility, particularly in papillary thyroid carcinoma." (PMID 39928612, 2025). "Some authors found difference in expression of Galectin 3 between papillary carcinoma, and its follicular variant, compared to follicular carcinoma." (PMID 26503236, 2015). "Further, expression of Galectin-3 in papillary carcinoma and follicular variant of papillary carcinoma was notably higher than in follicular adenoma (p = .000; p = .001; respectively)." (PMID 26503236, 2015). "In this study, we assessed four immunohistochemical markers, CK19, TG, Ki67 and galectin-3, and evaluated their diagnostic significance for papillary thyroid carcinoma in the northeastern region of China." (PMID 22188859, 2011). "Specific genetic variants of LGALS3 influence the risk of developing TC, and its role in the invasiveness of BRAF-mutated papillary thyroid carcinoma highlights its potential as a therapeutic target in tumor progression." (PMID 39928612, 2025). "In another study in the follicular epithelial cells with papillary carcinoma-like nuclear features in HT, galectin-3, CK19, and HBME-1 were strongly and diffusely positive in 17–87% of the cases." (PMID 33991306, 2021). "Individual statistical validation of HBME-1, galectin-3 expression, and BRAF V600E mutation in differentiating among papillary thyroid carcinoma, papillary thyroid hyperplasia, follicular adenoma, and follicular carcinoma." (PMID 34934597, 2021). "Galectin-3 modulates cell growth via galactosidase-binding protein, which is correlated with occurrence and metastasis of papillary thyroid carcinoma." (PMID 32612576, 2020). "Galectin-3 helped in the preoperative diagnosis of 100% (23/23) follicular adenomas, 75% (21/28) papillary carcinomas and 33.3% (3/9) follicular carcinomas." (PMID 28811803, 2017). "Galectin-3, (Gal-3) appears to be necessary for the maintenance of transformed thyroid papillary cancer (PTC) cell lines in vitro." (PMID 28383480, 2017). "In the thyroid gland, Galectin 3 (Gal-3) plays a significant role in the pathogenesis of well-differentiated carcinoma, particularly in papillary carcinoma." (PMID 28471415, 2017). "Papillary thyroid cancer cell line B-cpap and anaplastic thyroid cancer cell line 8305c were chosen to knock down Galectin-3." (PMID 29254179, 2017). "In papillary thyroid cancer cells, citrus pectin also displayed a dose-dependent inhibition to the binding of Galectin-3 to human umbilical vein endothelial cells." (PMID 29254179, 2017). "A papillary thyroid cancer cell line (B-cpap) and an anaplastic thyroid cancer cell line (8305c) were transfected with short-hairpin RNA against Galectin-3 (Gal-3-shRNA)." (PMID 29254179, 2017). "Although there existed no changes in the protein levels of Cav-1 between control cells or Galectin-3 knockdown cells, a co-localization of Galectin-3 (red) and Cav-1 (green) was found in papillary thyroid carcinoma tissue." (PMID 29254179, 2017). "For discriminating follicular variant of papillary carcinoma from follicular adenoma or carcinoma, best combinations were CK19 with Galectin 3, and CD56 with HBME1, respectively." (PMID 26503236, 2015). "Combining small molecule inhibition of galectin-3 and doxorubicin treatment of thyroid papillary cancer and cell lines increased drug response and apoptosis." (PMID 22039439, 2011). "Positive immunoexpression of CK-19, Galectin-3, HBME-1, and CD-44 improves the diagnostic accuracy of papillary thyroid cancer." (PMID 21052476, 2010). "Studies demonstrated the positivities of galectin-3 in 100% of papillary carcinomas, 90–100% of follicular carcinomas, 50–80% of medullary carcinomas, 0–33% of follicular adenomas and 0–38% of nodular goitres." (PMID 12698188, 2003).